TGFBR1 (transforming growth factor beta receptor 1)
Diseases named in the same sentence as TGFBR1 in open-access papers (continued):
Sharing a sentence is not in itself a finding about the gene and the disease.
aneurysm (12 papers, 2013 to 2025). Bulging or ballooning in an area of an artery secondary to arterial wall weakening. "In line with the clinical presentation of the patients in this study, several TAAD disease genes (e.g., SMAD3 and TGFBR1) are associated with a broad phenotypic spectrum including aneurysms/dissections of other arteries in addition to the aorta." (PMID 41056017, 2025). "Further investigation is required to confirm this observation in aortic SMCs of TAAD patients with other TGFBR1 mutations and with mutations in other aneurysm‐related genes." (PMID 31475485, 2019). "One of the most unambiguous indications that TGF‐β signaling plays a major role in aneurysm pathogenesis was provided by the finding that TGFBR1/2 mutations result in LDS." (PMID 29392890, 2018). "Notably, among the differentially expressed mRNAs predicted to be targeted by the differential miRNAs, were some genes previously experimentally identified to be involved in aneurysm formation or loss of vessel cells, such as TGFBR1, MMPs and IL18 etc.." (PMID 24079748, 2013). "Using CT or MRI, 3D reconstruction of images from the head to pelvis is needed to identify arterial tortuosity, present in most individuals with a TGFBR1/2, TGFB2, or SMAD3 mutation, and aneurysms in the rest of the arterial tree." (PMID 29392890, 2018). "Furthermore, higher plasma levels of TGF-beta 1 could also be an effect of altered binding ability to its receptors, TGFBR1 and TGFBR2, caused by the occurrence of genetic variants in these receptors that were previously associated with aneurysm development." (PMID 37569462, 2023).
bladder cancer (11 papers, 2004 to 2025). "Previous studies have implicated TGFBR1 polymorphic variants in bladder cancer risk and prognosis." (PMID 40433389, 2025). "TGF-β1-induced sumoylation of TGFBR1 is a prerequisite for induction of the epithelial–mesenchymal transition in bladder cancer cells." (PMID 31842336, 2019). "According to the same study, however, the levels of TGFBR1 in urine sediments of bladder cancer patients were decreased, with a concomitant increase of TGF-β1, which indicates independent mechanisms of TGF-β1 signaling in cancer and immune cells." (PMID 31842336, 2019). "There, a loss of TGF-β1 receptors, TGFBR1 and TGFBR2, correlated with the invasive tumor stage, high grade, and lymphovascular invasion while enhanced TGF-β1 levels in bladder cancer tissues and plasma of patients were associated with tumor invasiveness." (PMID 31842336, 2019). "E12A-containing HNRPLL regulates expressions of cyclin D1 and transforming growth factor beta receptor 1 (TGFBR1) to promote cell proliferation in kidney and bladder cancers." (PMID 30619092, 2018). "For bladder cancer, we selected TGFBR1 and for breast TGFBR2 due to their tissue-specific expression profiles." (PMID 28775339, 2017). "Interestingly, the expression of TGF-β1 and TGFBR1 in peripheral blood mononuclear cells (PBMNCs) of bladder cancer patients is increased compared with healthy individuals, which coincides with the role of TGF-β1 signaling in bladder cancer immunity." (PMID 31842336, 2019). "This process is reversed by SENP2 (SUMO-specific protease-2), which removes SUMO from TGFBR1, thereby inhibiting TGF-β1-induced EMT, resulting in inhibition of the invasion of bladder cancer cells in vitro and tumor metastasis in vivo." (PMID 31842336, 2019). "Our simulation results suggest that when E2F1, TGFBR1, and FGFR1 are simultaneously active, bladder cancer cells become highly invasive (EMT = 3)." (PMID 28775339, 2017).
endometrial cancer (11 papers, 2016 to 2025). Primary or metastatic malignant neoplasm involving the endometrium (mucous membrane that lines the endometrial cavity). "Upon eIF4E elevation in endometrial carcinoma, TGFBR1 induced HEC-1A cells to undergo endothelial-to-mesenchymal transition (EMT)." (PMID 40630212, 2025). "They found that Pten/Tgfbr1 double knockout mice developed severe endometrial lesions that progressed more rapidly than those resulting from conditional deletion of Pten alone, suggesting that TGF-β signaling suppresses endometrial carcinoma progression." (PMID 30510261, 2018).
multiple self-healing squamous epithelioma (11 papers, 2014 to 2025). "Reported pathogenic variants in TGFBR1 resulting in Ferguson-Smith syndrome are truncating or missense variants." (PMID 35359366, 2022). "Recently, TGFBR1 nonsense mutations have been identified in patients with multiple self-healing squamous epithelioma (MSSE, MIM 132800)." (PMID 24587008, 2014). "Additionally, loss-of-function mutations in TGFBR1 can cause a rare familial type of skin cancer known as Multiple Self-healing Squamous Epithelioma (MSSE)." (PMID 40612107, 2025). "However, distinct point mutations in TGFBR1, which spontaneously activate TGF-β signaling, have been reported as the cause of multiple self-healing squamous epithelioma, also known as Ferguson–Smith disease." (PMID 34456753, 2021). "Missense and truncating variants in the STK domain of the TGFBR1 gene induce LDS and multiple self-healing squamous epithelioma (MSSE), presumably through the dominant negative (DN) and haploinsufficiency (HI) effects, respectively." (PMID 31915033, 2020).
atherosclerosis (10 papers, 2013 to 2025). A disease characterized by the build-up of fatty material and calcium deposition in the arterial wall resulting in partial or complete occlusion of the arterial lumen. "In human VSMCs, we found LPA signals via TGFBR1 to stimulate genes associated with the initiation of atherosclerosis." (PMID 33923651, 2021). "When given at the time of atherosclerosis induction to ApoE null mice, 7C1-based delivery of Tgfbr1/2 siRNAs resulted in suppression of atherosclerotic plaque growth with virtually no inflammation, characteristic of this model, evident in the arteries." (PMID 37325472, 2023). "Here we focused on five genes (Tgfbr1, Zeb1, Hdac2, Rab5a, and Ets1), which were all identified by miFDR alone, and discussed their potential roles in the context of diesel particle exposure and atherosclerosis." (PMID 24564975, 2013).
cardiac hypertrophy (10 papers, 2019 to 2025). "We observed that silencing of the TGFBR1 gene inhibited cardiac hypertrophy in HFpEF mice (see Part 3.2), primarily evidenced by reduced ventricular wall thickness, heart mass, and cardiomyocyte cross-sectional area." (PMID 40880411, 2025). "To clarify the role of TGFBR1 gene silencing in HFpEF, we analyzed its effects on cardiac hypertrophy and fibrosis." (PMID 40880411, 2025). "In the present study, we found that silencing TGFBR1 inhibited myocardial hypertrophy both in vivo and in vitro." (PMID 40880411, 2025). "Mechanistically, we found that TGFBR1 gene silencing decreased myocardial collagen synthesis through the Smad2/3 signaling pathway and inhibited cardiac hypertrophy through the p38/MAPK–JNK1/2 signaling pathway in HFpEF mice." (PMID 40880411, 2025). "Silencing of the TGFBR1 gene improved cardiac function in HFpEF mice by attenuating cardiac fibrosis, reducing myocardial hypertrophy, and ameliorating myocardial remodeling." (PMID 40880411, 2025). "In the present study, we found that TGFBR1 gene silencing inhibited cardiac hypertrophy in HFpEF mice by suppressing the TAK1–P38/MAPK–JNK1/2 signaling pathway, and similar results were observed in vitro." (PMID 40880411, 2025). "Conditional deletion of TGFBR1 from fibroblasts significantly attenuates the pressure overload-induced cardiac hypertrophy and enhanced the ventricular function." (PMID 36843918, 2023). "At the same time, the microRNA-15 family has been reported to regulate myocardial hypertrophy and fibrosis by targeting TGFBR1." (PMID 32394311, 2020). "At the mechanistic level, TGFBR1 gene silencing led to a reduction in myocardial collagen synthesis through the Smad2/3 signaling pathway and an inhibition of cardiac hypertrophy through the mitogen-activated protein kinase (MAPK) signaling pathway in HFpEF mice." (PMID 40880411, 2025). "The effects of cardiomyocyte-specific Tgfbr1 knockdown have been studied in a murine model and correspond to our study outcomes: cardiac alterations were restricted to cardiac fibrosis, with minimal impact on cardiac hypertrophy or function." (PMID 38725830, 2024). "The specific knockdown of Smad2/3 in activated fibroblasts can reduce the extent of cardiac fibrosis after pressure overload but cannot reverse myocardial hypertrophy and heart failure, whereas the specific knockdown of TGFBR1/2 can alleviate both cardiac fibrosis and hypertrophy." (PMID 36787190, 2023). "In addition, deletion of TGFBR1 ameliorates the cardiac dysfunction, cardiac hypertrophy, and collagen deposition induced by MI." (PMID 36843918, 2023). "However, the role of TRAF6 in TGFBR1 regulation of TAK1-mediated cardiac hypertrophy and PANoptosis remains unclear." (PMID 40880411, 2025). "Moreover, 12 weeks after aortic constriction, Tgfbr1/2 knockout mice demonstrated reduced ventricular fractional shortening, preserved diastolic function and reduced cardiac hypertrophy, highlighting the targeting of the TGF-β pathway as a viable strategy to reduce cardiac fibrosis." (PMID 35326728, 2022). "Overall, the beneficial effects of TGFBR1 gene silencing on ameliorating myocardial remodeling in HFpEF mice primarily result from the inhibition of TAK1-mediated PANoptosis and cardiac hypertrophy." (PMID 40880411, 2025). "Some studies have indicated that TGFβ1 can activate TAK1 through the TGFBR1/2 complex, with activated TAK1 promoting cardiac hypertrophy via the p38/MAPK-JNK1/2 signaling pathway." (PMID 40880411, 2025). "Additionally, TGFBR1 gene silencing significantly reduced the HFD + L-NAME–induced increases in diastolic and systolic blood pressure and NT-proBNP, a marker of HF, and improved exercise intolerance, cardiac hypertrophy, and pulmonary edema." (PMID 40880411, 2025).
cervical carcinoma (10 papers, 2017 to 2025). A carcinoma arising from either the exocervical squamous epithelium or the endocervical glandular epithelium. "The hazard ratio values of TGFB1 and TGFBR1 were both > 1, indicating these as high-risk genes in cervical cancer." (PMID 39312339, 2024). "TGFBR1 is also often overexpressed in cervical cancer, and has been implicated in the regulation of angiogenesis, invasion, and metastasis." (PMID 37894282, 2023). "TGFB1 and TGFBR1 are known as high-risk factors for cervical cancer." (PMID 39312339, 2024). "Furthermore, TNFRSF12A (TWEAK-R), NT5E (CD73), and TGFB1/TGFBR1 were genes where low expression was significantly associated with increased survival in both cervical cancer and HNSCC, demonstrating that high expression of these immune genes is detrimental to outcome." (PMID 36575316, 2023). "Knockdown of TGFBR1 in ST2 cells accelerates adipogenic differentiation; Let-7a inhibits cell proliferation by targeting TGFBR1 in cervical carcinoma." (PMID 41514724, 2025). "Higher expression of EGFR/TGFBR1 has been shown to promote cervical cancer." (PMID 37894282, 2023). "For instance, DANCR competitively sponges the 3′UTR of transforming growth factor beta receptor 1 (TGFBR1) mRNA in cervical cancer cells, which blocks miR-665 from binding to and degrading TGFBR1 and promotes the TGFBR1-mediated oncogenic ERK (extracellular regulated protein kinases)/SMAD pathway." (PMID 31799189, 2019). "MiR-665 has been shown to inhibit cervical cancer malignant progress by targeting two cell surface receptors, EGFR and TGFBR1." (PMID 37894282, 2023). "Consistent with previous reports, TGFBR1 was shown to function as a tumor oncogene in NSCLC and had lower expression in uterine cervix carcinoma." (PMID 29371929, 2017).
breast tumor (9 papers, 2015 to 2024). "Conditioned medium from breast tumor cells also enhanced the expression of N-cadherin in BM-MSCs, but inactivation of TGF-β type 1 receptor (TGFBR1) with SB505124 and TGFBR1 knockdown abolished the increase in N-cadherin expression." (PMID 34093853, 2021). "Moreover, we were able to show an increase of TGFBR1 and TGFBR2 mRNA expression in breast tumors from Elovl5−/− mice compared to tumors from Elovl5+/+." (PMID 36056008, 2022).
fibrosis (9 papers, 2010 to 2025). the formation of excess fibrous connective tissue in an organ or tissue in a reparative or reactive process. "Some of the most significantly activated canonical pathways included hepatic fibrosis/hepatic stellate cell activation (CD14, COL1A1, FGFR2, IGFBP3, MMP2, and TGFBR1), and p38 MAPK signaling pathways (CREB1, PLA2G2A, TGFBR1)." (PMID 20540791, 2010). "It did not appear that these changes in expression were directly associated with TGFβ signaling and furthermore, an inhibitor to the TGFβR1 (activin-like kinase 5, ALK-5) could not completely attenuate bleomycin-induced fibrosis in mice." (PMID 23565148, 2013).
myocardial infarction (9 papers, 2014 to 2025). Gross necrosis of the myocardium, as a result of interruption of the blood supply to the area, as in coronary thrombosis. "Inhibition of TGFBR1/ALK5 also reduces myocardial infarction-induced systolic dysfunction and left ventricular remodeling in rats." (PMID 31884871, 2020). "A previous study revealed that the inhibition of TGFBR1 results in significant amelioration of deleterious cardiac remodeling following myocardial infarction." (PMID 24940402, 2014). "A study based on a tag-based digital gene expression profiling (DGE) system showed that the mechanism of ventricular remodeling induced by myocardial infarction by BYHWD treatment may be closely related to transforming growth factor beta receptor-1, junctophilin-2, and monocyte." (PMID 34422208, 2021). "Calycosin can ameliorate myocardial infarction-induced inflammation and fibrosis via activation of PI3K-AKT-IκB kinase α/β (IKKα/β) in heart failure rats and transforming growth factor-beta receptor 1 (TGFBR1) pathways in heart failure mice." (PMID 36408254, 2022). "One study of left ventricular dysfunction after acute myocardial infarction reported a panel of three genes (TNXB, TGFBR1, and LTBP4) that could potentially improve the prediction of post-myocardial infarction heart failure." (PMID 34071145, 2021).
thoracic aortic aneurysm (9 papers, 2012 to 2025). An aneurysm formed in the wall of the proximal portion of the descending aorta proceeding from the arch of the aorta. "Evidence from the spectrum of TGFBR1 mutations in MSSE shows that truncating mutations detected in patients with thoracic aortic aneurysms in the course of diagnostic testing must be viewed with caution and not used as the basis of predictive tests for relatives." (PMID 33256177, 2020). "Selective deletion of Alk5 or Tgfbr1 in smooth muscle cells of adult mice results in thoracic aortic aneurysm and rupture in male mice, while female mice present only a subclinical phenotype with mild fragmentation of the aortic elastic lamellae." (PMID 28708846, 2017). "Indeed, pathogenic variants or deficiency of TGF-β pathway genes, including TGFB2, TGFB3, TGFBR1, TGFBR2, and SMAD3, confer risks for aortic destruction and thoracic aortic aneurysm formation." (PMID 38916960, 2024). "Previous data from literature indicated the contribution of TGFBR1 and TGFBR2 genes in thoracic aortic aneurysms and dissections." (PMID 30255099, 2018).
diabetes (8 papers, 2014 to 2025). "It has been found that vascular endothelial growth factor A (VEGFA) and transforming growth factor beta receptor 1 (TGFBR1) are upregulated in diabetes." (PMID 40166052, 2025). "For hsa-miR-548k, main targets involved in diabetes-related pathways were identified, including TGFBR1, STAT1, NFKB1, MAPK1, and STAT5A." (PMID 40788916, 2025). "However, as Smad2 also plays an essential role in the glucose-stimulated release of insulin in β cells 16, targeting Smad3 but not upstream TGFBR1 in islets (β cells) may be more favorable for cell replacement treatment of diabetes." (PMID 34987651, 2022).
osteoarthritis (8 papers, 2014 to 2022). A noninflammatory degenerative joint disease occurring chiefly in older persons, characterized by degeneration of the articular cartilage, hypertrophy of bone at the margins and changes in the synovial membrane. "Nicolai’s study found that the overexpression of SMURF2 reduced the levels of RUNX2 and TGFBR1 in an osteoarthritis system, and our investigation added direct information about the relationship between RUNX2 and TGFBR1." (PMID 36611957, 2022).